IGHV3-30 (immunoglobulin heavy variable 3-30)
Description:
V region of the variable domain of immunoglobulin heavy chains that participates in the antigen recognition. Immunoglobulins, also known as antibodies, are membrane-bound or secreted glycoproteins produced by B lymphocytes. In the recognition phase of humoral immunity, the membrane-bound immunoglobulins serve as receptors which, upon binding of a specific antigen, trigger the clonal expansion and differentiation of B lymphocytes into immunoglobulins-secreting plasma cells. Secreted immunoglobulins mediate the effector phase of humoral immunity, which results in the elimination of bound antigens. The antigen binding site is formed by the variable domain of one heavy chain, together with that of its associated light chain. Thus, each immunoglobulin has two antigen binding sites with remarkable affinity for a particular antigen. The variable domains are assembled by a process called V-(D)-J rearrangement and can then be subjected to somatic hypermutations which, after exposure to antigen and selection, allow affinity maturation for a particular antigen.
Synonyms: IGHV330; VH
Tractability: Antibody: its Gene Ontology location is reachable by antibodies, with high confidence; UniProt places it where antibodies can reach, with medium confidence; UniProt predicts a signal peptide or a membrane-spanning region.
Gene: Immunoglobulin variable (V) gene on chromosome 14 (106,335,082 to 106,335,613, reverse strand). Ensembl gene ENSG00000270550.
Subcellular location: Secreted; Cell membrane
Pathways (Reactome):
Immune System: Antigen activates B Cell Receptor (BCR) leading to generation of second messengers; CD22 mediated BCR regulation; Classical antibody-mediated complement activation; FCERI mediated Ca+2 mobilization; FCERI mediated MAPK activation; FCERI mediated NF-kB activation; FCGR activation; Fc epsilon receptor (FCERI) signaling; Immunoregulatory interactions between a Lymphoid and a non-Lymphoid cell; Initial triggering of complement; Regulation of Complement cascade; Regulation of actin dynamics for phagocytic cup formation; Role of LAT2/NTAL/LAB on calcium mobilization; Role of phospholipids in phagocytosis
Disease: FCGR3A-mediated IL10 synthesis; FCGR3A-mediated phagocytosis; Potential therapeutics for SARS
Hemostasis: Cell surface interactions at the vascular wall
Vesicle-mediated transport: Scavenging of heme from plasma
Gene Ontology:
Molecular function: antigen binding
Biological process: immune response; immunoglobulin mediated immune response
Cellular component: extracellular region; plasma membrane
Homologues: Paralogues in human: IGHV3-33 (98% identical), IGHV3-23 (87% identical), IGHV3-7 (86% identical), IGHV3-74 (86% identical), IGHV3-43 (85% identical), IGHV3-48 (85% identical), IGHV3-64 (84% identical), IGHV3-66 (84% identical), IGHV3-21 (83% identical), IGHV3-64D (83% identical), IGHV3OR16-13 (83% identical), IGHV3-11 (82% identical), and 65 more.
Diseases named in the same sentence as IGHV3-30 in open-access papers:
IGHV3-30 is named in the same sentence as 1 disease in open-access papers, as found by Europe PMC text mining. Sharing a sentence is not in itself a finding about the gene and the disease. The quoted sentences say what the papers report.
COVID-19 (1 paper, 2021). A disease caused by infection with severe acute respiratory syndrome coronavirus 2. "Our IPA analysis found that the IgG component genes, IGHG3, IGHG4, and IGHV3-30 are upregulated in the lungs of severe COVID-19 patients." (PMID 34899680, 2021).